FOXO1 (forkhead box O1)
Diseases named in the same sentence as FOXO1 in open-access papers (continued):
Sharing a sentence is not in itself a finding about the gene and the disease.
breast carcinoma (continued). "In turn, in other types of cancer, the increased transcriptional activity of FOXO1 has also been demonstrated, e.g., in squamous cell carcinoma of the esophagus and breast cancer." (PMID 36830954, 2023). "Dysregulation of FOXO1 is thought to contribute to the progression of a variety of cancers, including breast carcinoma." (PMID 36835085, 2023). "We have previously shown the role of a polyphenolic mixture fermented by SV-53 in the chemoprevention of mammary carcinoma and controlling breast cancer stem cells by increasing miR-145 and FOXO1." (PMID 37834058, 2023). "A previous study reported that AGK can suppress FOXO1 transcriptional activity in breast cancer cells 27, similar to our study." (PMID 35910796, 2022). "The current study proposes to determine the correlation between methylation and expression of FOXO1 in breast cancer biopsy as compared to adjacent normal tissue." (PMID 35309123, 2022). "Strikingly, inhibition of DNMT3B reduces TIMP3 methylation levels and enhances TIMP3 protein levels, thus modulating the STAT1/FOXO1 pathway in breast cancer." (PMID 36061358, 2022). "Conclusion: we in our study report the tumor suppressive role of FOXO1 in case of Indian breast cancer patients and our data suggest it to exhibit prognostic importance." (PMID 35309123, 2022). "Previous reports found that knockdown of miR-29c in breast cancer cells inhibited FOXO1 expression but promoted the proliferation, migration, and invasion of breast cancer cells." (PMID 35433915, 2022). "The fold change of 88 downregulated cases was examined to be 5.16 the expression of FOXO1 in breast cancer tissue was 1.16 ± 0.02 (Mean ± SE) and in the normal tissue was 1.95 ± 0.07 (Mean ± SE) (p < 0.0001)." (PMID 35309123, 2022). "Further, Guttilla and White demonstrated that the overexpression of FOXO1 strongly inhibits cell proliferation and induced apoptosis in breast cancer MCF7 cell line." (PMID 36539739, 2022). "The expression of FOXO1 at the mRNA level was detected in case of breast cancer and adjacent normal tissue." (PMID 35309123, 2022). "Though the expression of FOXO1 is largely examined in breast cancer, the regulation of FOXO1 by miRNA is yet to be explored." (PMID 36539739, 2022). "We suggest that FOXO1 can be taken as a biomarker in the case of breast cancer and further research can be carried out to find therapeutic strategies in targeting the FOXO1 gene." (PMID 35309123, 2022). "FOXO1 is defined to play tumor suppressive role in various malignancies including breast cancer and its Dysregulation is frequently reported." (PMID 35309123, 2022). "Keeping this as background, the present study demonstrates the role of exogenous oncomiRs on the expression of FOXO1 in breast cancer cell line and its effect on cancer cell proliferation." (PMID 36539739, 2022). "Currently, miR-27a, miR-96, and miR-182 are known oncomiRs in breast cancer which coordinately reduce the expression of FOXO1." (PMID 36539739, 2022). "In breast cancer, miR-221 can work through both modulating the estrogen receptor gene, and FOXO1 expression." (PMID 34905088, 2022). "The decreased nuclear and cytoplasmic expressions of FOXO1 in the case of breast cancer have been reported in the previous studies." (PMID 35309123, 2022). "In conclusion, we have designed and synthesized self-assembled bDNA nanostructures bearing microRNA sequences as functional unit in all four overhangs that target intracellular tumor suppressor gene FOXO1 in MCF7 breast cancer cell line." (PMID 36539739, 2022).
breast carcinoma (continued). "Studies have shown that FOXO1 plays an anti-tumor role in many solid tumors, such as breast cancer, prostate cancer, digestive system cancer and other tumors." (PMID 36290822, 2022). "Despite substantial research on FOXO1 activity, the regulation of FOXO1 expression particularly in breast cancer is poorly understood." (PMID 36539739, 2022). "Further, FOXO1 is identified as a key tumor suppressor protein in breast cancer that regulates cell proliferation, invasion, metastasis and survival." (PMID 36539739, 2022). "Correlation analysis between FOXO1 methylation and FOXO1 protein expression in stratification by various clinical characteristics of Breast cancer patients from North India." (PMID 35309123, 2022). "In this study, we propose that PLGA-QNPs, a representative Forkhead box protein O1 (FoxO1)-activating nanoformulation, are a potential candidate against cervical and breast cancer." (PMID 35890222, 2022). "Correlation study of FOXO1 Promoter Methylation status with clinical parameters of Breast Cancer Patients." (PMID 35309123, 2022). "FOXO1 is a master regulator that regulates cell cycle proliferation, invasion, metastasis and in several cancers including breast cancer." (PMID 36539739, 2022). "In the current study, we examined the expression level of FOXO1 in 127 breast cancer tissues taken along with adjacent normal tissues from the Indian female breast cancer patients." (PMID 35309123, 2022). "This study reports the tumor-suppressive role of FOXO1 in the case of Indian breast cancer patients and our data also suggested FOXO1 exhibited prognostic importance." (PMID 35309123, 2022). "OncomiRNAs like miR-27a, miR-96, and miR-182 are upregulated in breast cancer and they collectively downregulate the expression of FOXO1." (PMID 36539739, 2022). "Unsurprisingly, there is prior evidence to suggest that DNMT3B affects the progression of breast cancer by targeting the STAT1/FOXO1 pathway." (PMID 36061358, 2022). "Among FoxO members, FoxO1 plays important roles in cell dissemination and anticancer drug resistance in breast cancer due to its direct regulation of the transcription of the metastatic factors MMP-1 and the drug efflux pump multidrug resistance 1 (MDR1)." (PMID 36077661, 2022). "In the current study, self-assembled bDNA nanostructures has been explored to carry miR-27a, miR-96, miR-182 in the overhangs to downregulate the expression of FOXO1 in breast cancer MCF7 cell line." (PMID 36539739, 2022). "PEBP has been shown to inhibit PI3K/AKT activation in three different breast cancer cell lines, potentially affecting miR-145 through FOXO1." (PMID 34299605, 2021). "Work by Li and colleagues reflects the favorable properties of miR-29c in breast cancer by regulating the TIMP/STAT1/FOXO1 pathway." (PMID 34035375, 2021). "Growing evidence has shown that FOXO1 is downregulated in various human malignancies which include cervical cancer, breast cancer, and endometrioid endometrial cancer." (PMID 34552661, 2021). "In the meantime, the interaction between FOXO1 and miRNAs has been detected in some malignancies, such as bladder cancer and breast cancers." (PMID 34035814, 2021). "Regarding FOXO1, it has long been reported that FOXO1 expression is downregulated in cervical cancer, kidney cancer, breast cancer, prostate cancer, endometrial cancer, and ovarian cancer." (PMID 34825509, 2021). "For example, cell division cycle 25A (CDC25A) directly regulates the transcription of matrix metalloproteinase 1 through FOXO1, thereby enhancing the invasive ability of breast cancer cells." (PMID 34123834, 2021). "Recently, TRIB3 was reported to regulate the β-catenin pathway in colorectal cancer and to suppress forkhead box protein O1 (FOXO1) phosphorylation in breast cancer by helping to maintain cancer stem cells (CSCs)." (PMID 33334065, 2020).
breast carcinoma (continued). "The inhibition of these mRNAs led to the restoration of FoxO1 expression that in turn contributes to the transformation or maintenance of an oncogenic state in breast cancer cells." (PMID 32766159, 2020). "For instance, the p21-activated kinase (PAK1, a downstream target of PI3K) can bind and phosphorylate FOXO1 directly to prevent its nuclear translocation in breast cancer." (PMID 32372224, 2020). "With respect to cell migration, an activator of CDK1 and CDK2, Cdc25A phosphatase can enhance FOXO1 stability to promote MMP-1-mediated metastasis in breast cancer." (PMID 32372224, 2020). "Upregulation of MALAT1 in breast cancer induces EMT and decreases trastuzumab sensitivity in HER2+ breast cancer, and the mechanism is associated with PI3/Akt-mediated FOXO1 nuclear retention." (PMID 32708561, 2020). "The upregulation of p57 and FOXO1 by diosgenin was further increased by Skp2 siRNA transfection in breast cancer cells." (PMID 32626765, 2020). "To determine the molecular mechanism behind MALAT1 regulation, we examined if FOXO1 can bind to the MALAT1 promoter in breast cancer cells." (PMID 32708561, 2020). "To investigate in more detail the role of FOXO1 and FOXO3 genes in breast cancer, we also performed a log rank test to analyse the relationship between FOXO1 and FOXO3 protein expressions and metastasis-free survival (MFS)." (PMID 32332845, 2020). "To confirm this data, we also measured the expression of Skp2 downstream targets, including p57 and FOXO1, in breast cancer cells treated with various doses of diosgenin for 72 hours." (PMID 32626765, 2020). "The microRNA miR-29c also represses FOXO1 expression to facilitate breast cancer cell growth, migration and invasion, whilst miR-135b inhibits FOXO1 expression to promote cell proliferation and invasion in osteosarcoma." (PMID 32372224, 2020). "We found in this study that FOXO1 plays a regulatory role in mediating MALAT1 expression in breast cancer cells via the PI3/Akt pathway." (PMID 32708561, 2020). "In breast cancer cells, FoxO1 expression was directly regulated by three miRNAs (miR-27a, miR-96, and miR-182)." (PMID 32766159, 2020). "We also showed in our earlier study that phosphorylation of Akt protein at ser473 mediates nuclear export of FOXO1 and loss of p27kip1 reduced sensitivity of trastuzumab in HER2+ breast cancer cells." (PMID 32708561, 2020). "Obviously, we can see that NF1, BRCA1, FOXO1, PTEN, CAV1 and WT1 are linked with breast cancer genes in PPI network or pathway network." (PMID 31760937, 2019). "In contrast to a role for FoxO1 in favoring drug-induced apoptosis is the evidence of increased nuclear FoxO1 levels and DNA binding activity in breast cancer cells resistant to doxorubicin." (PMID 30646603, 2019). "In a breast cancer cell model, including cells resistant to doxorubicin, miR-222 has been reported to confer drug resistance through FoxO1." (PMID 30646603, 2019). "Here the authors show that TRIB3 enhances breast cancer stemness through interaction with AKT to promote FOXO1 stability, which then increases SOX2 activity." (PMID 31844113, 2019). "In contrast, breast cancer cells exposed to BITC are reported to promote autophagic cell death through increased expression of the FOXO1 (forkhead box protein O1) pathway." (PMID 31003534, 2019). "More recently, an alternative mechanism played by FoxO1 and FoxO3 in lapatinib response of breast cancer cells has been reported." (PMID 30646603, 2019). "We firstly reported that miR-29c plays a significant role in suppressing the progression of breast cancers by targeting the TIMP3/STAT1/FOXO1 pathway." (PMID 29796115, 2018). "We firstly illustrated that miR-29c exerted its regulatory function in breast cancers by activating the TIMP3/STAT1/FOXO1 pathway." (PMID 29796115, 2018).
breast carcinoma (continued). "Together, the results demonstrate a suppressive role of miR-29c by targeting the TIMP3/STAT1/FOXO1 pathway in breast cancer cell proliferation, migration and invasion, and suggest that the loss of miR-29c might be a novel biomarker related to the progression of breast cancer." (PMID 29796115, 2018). "The RNA-binding protein Quaking (QKI) resulted in low levels of FOXO1 expression in breast cancer cells." (PMID 29796115, 2018). "This is firstly reported that miR-29c inhibited the proliferation, migration, invasion colony, and 3D growth of breast cancer cells by targeting TIMP3/STAT1/FOXO1 pathway." (PMID 29796115, 2018). "The competition between forkhead box protein O1 (FOXO1) and E‐cadherin (CDH1) for miR‐9 was reported wherein FOXO1 acted as a ceRNA resulting in inhibition of metastasis of breast cancer cells by inducing CDH1 expression." (PMID 29603582, 2018). "FOXO1 is an experimentally validated target of miR-182 in breast cancer and a target of miR-183 in non-small cell lung cancer." (PMID 30406026, 2018). "On the contrary, PRDX1 has a tumor promoting role in breast cancer, bladder cancer, oral squamous cell carcinoma, lung cancer, and esophageal squamous cell carcinoma through activation of NF-κB pathway, FOXO1-mediated pathway, and mTOR/p70S6K pathway." (PMID 30104402, 2018). "All together, these results suggest that miR-29c inhibits breast cancer by targeting the DNMT3B/TIMP3/STAT1/FOXO1 pathway." (PMID 29796115, 2018). "Astrocyte-elevated gene-1 (AEG-1) inhibited the expression of FOXO1 and promoted the progression of breast cancer." (PMID 29796115, 2018). "Acylglycerol kinase was reported to promote the growth of cells and tumorigenicity in breast cancer by inhibiting the expression of FOXO1.TIMP3 is a versatile extracellular regulator in cancers." (PMID 29796115, 2018). "In breast cancer cells treated with 5-fluorouracil, there is an accumulation of human antigen R (HuR), an RNA-binding protein which binds to and stabilizes FOXO1 mRNA to promote apoptosis." (PMID 29299162, 2017). "Negative regulation of FOXO1 in cellular migration or invasion has been reported in various types of cancer, including prostate, and breast cancer." (PMID 28099936, 2017). "FOXO1 is known to be regulated by miR-27a, miR-96, and miR-182 in breast cancer cells, SERPINB5 is regulated by miR-21, and STARD10 is regulated by miR-661." (PMID 28793339, 2017). "It is known that hsa-miR-96 is overexpressed in breast cancer and promotes tumor proliferation and invasion by suppressing transcription factors FOXO1 and FOXO3a." (PMID 28793339, 2017). "The previously performed experiments nominated AMPK and other mitotropic factors (PGC’s, FOXO1) as possible targets in human breast cancer." (PMID 26919657, 2016). "Among the miRNAs, miR-27a, miR-96, miR-182, and miR-183 suppressed FOXO1 expression in breast cancer, melanoma, and Hodgkin lymphoma." (PMID 25909227, 2015). "Taken together, our results suggest that FOXO1 plays a critical role in the pro-proliferative effect of AGK on breast cancer cells." (PMID 24886245, 2014). "miR-182 can target tumor suppressor gene FOXO1 and functions as oncogene in endometrial cancer and breast cancer." (PMID 24884732, 2014). "Previously, studies from our group identified the forkhead-family member, FOXO1, to play a role in drug-resistance and survival in breast cancer." (PMID 25062088, 2014). "We showed that depletion of FOXO1 restored the growth rate of AGK-silenced breast cancer cells, indicating that FOXO1 plays a critical role in the pro-proliferative effect of AGK on breast cancer cells." (PMID 24886245, 2014). "We also found that AGK expression inversely correlated with FOXO1 in the ten freshly collected clinical breast cancer samples (r = -0.721, P = 0.019)." (PMID 24886245, 2014). "Upregulation of GOLPH3 and an increase in proliferation and tumorigenicity has been correlated with the Akt-FoxO1 signaling pathway in breast cancer cells." (PMID 25104140, 2014).
breast carcinoma (continued). "Regulation of FOXO1 by miR-96 was confirmed previously in breast cancer, classical Hodgkin lymphoma as well as in endometrial carcinomas." (PMID 24260486, 2013). "In breast cancer cells, FOXO1 was coordinately targeted by miR-27a, miR-96, and miR-182, while the inhibition of each miRNA resulted in induced levels of FOXO1 and reduced breast cancer cell survival." (PMID 32309538, 2013). "The major events in the mechanism of NO induced apoptosis such as activation of catalase, PP2A and dephosphorylation of phosphorylated FOXO1 were also observed in MCF7 breast cancer cells." (PMID 23950968, 2013). "In agreement with our results, downregulation of FOXO1 in chicken embryo fibroblasts or inhibition of the transcriptional activity of FOXO3a in human breast cancer cells can promote transformation and tumor progression." (PMID 23029264, 2012). "For example, miR-27a, miR-96 and miR-182 can coordinately regulate the expression of FOXO1 by directly targeting the FOXO1 3′-UTR in breast cancer." (PMID 23029264, 2012). "Up-regulation of hsa-miR-96 results in down-regulations of transcriptional factor FOXO3a and FOXO1, and thus induces cell proliferation in human breast cancer." (PMID 22046296, 2011). "These three microRNAs, miR-27a, miR-96 and miR-182, were observed to be highly expressed in MCF-7 breast cancer cells, in which the level of FOXO1 protein is very low." (PMID 20815877, 2010). "So we focused on the effects of FOXO1 in breast cancer after co-cultured with adipocytes." (PMID 39135158, 2024). "This nanospheres can overcome the non-targeted defects of ordinary liposomes, significantly improve the uptake efficiency of luteolin, and play an anti-breast cancer role by significantly inhibiting the proliferation and migration of breast cancer cells and up-regulating the expression of FOXO1." (PMID 39314630, 2024). "Furthermore, we measured the expression of FOXO1 and KLF5 in different breast cancer cell lines and found that levels of FOXO1 were comparable to those of KLF5." (PMID 37588224, 2024). "Adipocytes might accelerate the progression of breast cancer by modulating FOXO1/miR-135b/ circCNIH4 /EMT axis and regulating copper homeostasis." (PMID 39135158, 2024). "Forkhead box class O 1 (FOXO1) promotes chemoresistance to doxorubicin in breast cancer." (PMID 37588224, 2024). "Additionally, our analysis indicated a positive correlation between FOXO1 and circCNIH4 in breast cancer cells and tissues." (PMID 39135158, 2024). "At the same time, adipocytes might promote breast cancer development through the FOXO1/miR-135b axis." (PMID 39135158, 2024). "The results appropriately supported our speculation that adipocytes stimulated breast cancer cell invasion and migration by FOXO1/miR-135b/circCNIH4 through EMT pathway and regulating copper homeostasis." (PMID 39135158, 2024). "Furthermore, the downregulation of FOXO1 has been found to suppress P21 and P27 expression, thereby promoting proliferation and tumorigenesis in the human breast cancer." (PMID 38436783, 2024). "However, rare studies had explored the relationship between FOXO1 and obesity in breast cancer patients." (PMID 39135158, 2024). "Adipocytes enhanced the migration of breast cancer and attenuated the effects of FOXO1." (PMID 39135158, 2024). "Furthermore, we studied the pathways related to miR-145, including FOXO1 and N-ras, in the breast cancer cell lines." (PMID 36835085, 2023). "In addition to FOXO3a, FOXO1 was also downregulated by miR-96-5p in breast cancer, suggesting that regulation of FOXO proteins by miRNA plays an important role in tumor invasiveness." (PMID 38136293, 2023). "Moreover, we demonstrated the role of PEBP in inhibiting breast cancer stemness by upregulating FOXO1 and downstream miR-145 in breast cancer cell lines." (PMID 36835085, 2023). "Furthermore, the percentage of FOXO1 protein downregulation was significant with Her2 neu status, tumor size, and histological grade of breast cancer." (PMID 35309123, 2022).